CCL5 (C-C motif chemokine ligand 5)
Diseases named in the same sentence as CCL5 in open-access papers (continued):
Sharing a sentence is not in itself a finding about the gene and the disease.
diabetes (continued). "In other disease models, chemokines are involved in the fibrosis process of injured tissues, much like CCL5 contributes to liver fibrosis in non-alcoholic fatty liver disease progression and CXCR4 contributes to cardiac fibrosis in diabetes." (PMID 31164836, 2019). "Further analysis focusing specifically on chemokines and their receptors also revealed a significant increase in the expression of CCL5 and CCL7 in rat retinas with 4 weeks of diabetes." (PMID 25329075, 2014). "CCL5 interacts with several chemokine receptors, such as CCR1, CCR3, and CCR5, to mediate its effects, extending to various pathological conditions, including inflammatory diseases, cancer, and metabolic disorders like diabetes." (PMID 39807180, 2025). "miRs from the let-7 family directly diminish the expression of MCP-1/CCL2 and RANTES/CCL5 cytokines, which are complicated in the progression of BBB inflammation that happens during traumatic brain injury, various forms of encephalitis and diabetes." (PMID 32766248, 2020). "In this study, benign prostate tissues of patients with T2D showed elevated expressions of CCL2 and CCL5 than samples of patients without diabetes." (PMID 33207809, 2020).
pancreatic cancer (59 papers, 2008 to 2025). "Circulating levels of C-C motif chemokine ligand 5 (CCL5) have been associated with an unfavorable prognosis in pancreatic cancer treated with capecitabine, the result being associated with a possible CCL5-induced immunosuppressive tumor microenvironment." (PMID 36233450, 2022). "Along similar lines, a retrospective analysis of transcriptomic data obtained from patient-derived pancreatic cancer samples outlined a positive correlation between high expression levels of CCL5 and poor overall survival." (PMID 40282185, 2025). "It has been proved that CCL5 reconfigures the TME to favor T cell infiltration in pancreatic cancer." (PMID 40475010, 2025). "CD73 can up-regulate CCL5 through the p38-STAT1 axis through the eAdo-A2aR signaling pathway, recruit Treg cells to pancreatic tumors, and cause inhibitory TME." (PMID 39188712, 2024). "This hydrogel complex downregulated CCL5 secretion of tumor cells, which contributed to an increase in M1 macrophages and elicited a T cell-mediated immune response, ultimately controlling pancreatic cancer in mice." (PMID 39114657, 2024). "Pancreatic tumors that are poorly differentiated produce higher levels of CCL5 and express more of its main receptor, CCR5, compared to well-differentiated and non-cancerous tissue." (PMID 39656086, 2024). "Previous reports demonstrated that the CCR5/CCL5 axis promotes a migratory and invasive phenotype in pancreatic cancer cells and Hodgkin’s lymphoma via tumour cell-intrinsic signalling of CCR5 on tumour cells." (PMID 38672174, 2024). "To validate the in vivo effects of the secretion of the inflammatory cytokines downstream of SRI (CCL5 and serpin E1) on islets in situ, we subcutaneously implanted pCDH-NC and pCDH-shSRI pancreatic cancer cells into nude mice." (PMID 39516378, 2024). "Conversely, CCL5 expression levels in the stroma were decreased in orthotopic pancreatic tumors of neutrophil-depleted mice, confirming TANs as a major source of CCL5 in the PDAC TME." (PMID 39261943, 2024). "CCL5, abundantly secreted in TANs, promotes the migration and invasion of pancreatic cancer cells and facilitates the recruitment of Treg cells." (PMID 39261943, 2024). "(A) Overall and disease-free Kaplan-Meier survival plots of pancreatic ductal adenocarcinoma (PDAC) patients segregated into high or low CCL5 gene expression levels within pancreatic tumors." (PMID 39656086, 2024). "As already discussed, CCL5 production by pancreatic cancer cells appears to increase Treg accumulation, which also express CCR5 at higher rates than effector T cells." (PMID 38339310, 2024). "In another study, a hydrogel nanoparticle complex, LPR@CHG, containing lipid-immune regulatory factor 5 mRNA/CCL5 siRNA (LPR) nanoparticle complexes coated with chitosan/HTCC/glycerophosphate was designed as a potential pancreatic cancer treatment." (PMID 39114657, 2024). "Neutrophils isolated from orthotopically implanted pancreatic tumors in mice (mouse TANs) abundantly secreted CCL5, MIP1-gamma, and TNFRII compared to circulating PB neutrophils." (PMID 39261943, 2024). "In pancreatic cancer, the secretion of CCL5 by tumor cells critically contributes to the recruitment of Treg cells." (PMID 37291128, 2023). "The interaction between CCR5 and CCL5 results in increased migration and invasiveness of pancreatic cancer cells." (PMID 37371612, 2023). "CD73 transcriptionally upregulates CCL5 through tumor cell-autocrine adenosine–Adora2a signaling-mediated activation of the p38–STAT1 axis, recruiting Tregs to pancreatic tumors and causing an immunosuppressive microenvironment." (PMID 37291128, 2023). "In pancreatic ductal adenocarcinoma, the FoxP3 expression was demonstrated in pancreatic cancer cells with tumor-infiltrating Tregs through the FoxP3/C-C motif chemokine ligand 5 (CCL5)/C-C motif chemokine receptor 5 (CCR5) pathway." (PMID 37569676, 2023).
pancreatic cancer (continued). "In a recent study, the combined blockade of PD-L1 and CCL-5, which recruits Treg cells, strengthened antitumor effects in a xenograft model of pancreatic cancer." (PMID 37127565, 2023). "In the current study, we found that CD73 activates the p38–STAT1 axis through tumor cell-autocrine adenosine–Adora2a signaling, which results in the upregulation of CCL5 and further Treg recruitment in pancreatic cancer." (PMID 37291128, 2023). "By performing a K–M survival analysis, CCL5 and CCL14 are associated with survival in patients with pancreatic cancer." (PMID 37741887, 2023). "In addition, high tissue or plasma levels of CCL5 correlate with unfavorable outcomes in pancreatic cancer patients." (PMID 39114657, 2024). "As anticipated, in both sets of nude mice (those harboring pCDH-NC and those harboring pCDH-shSRI pancreatic cancer cells), intratumoral administration of CCL5 and serpin E1 led to elevated fasting blood glucose levels and reduced fasting insulin levels compared with those in the PBS group." (PMID 39516378, 2024). "Importantly, however, they showcase that pancreatic cancer cells can express CCL5 prior to co-culture." (PMID 38339310, 2024). "CCL4, CCL5, CXCL9, and CXCL10 are associated with CD8+ T cells in pancreatic cancer." (PMID 38887558, 2024). "Thus, while support cells in the PDAC TME, such as myeloid cells and TAMs, can express CCL5 later on, pancreatic cancer cells’ ability and early expression of the chemokine lead to classifying it as produced by malignant epithelial cells." (PMID 38339310, 2024). "In addition, data from TCGA demonstrated that CCL5 expression positively correlated with FOXP3 expression in pancreatic cancer." (PMID 37291128, 2023). "Previous reports showed that CXCL9, CXCL10, and CCL5 could mark T cell–inflamed phenotype of pancreatic cancer." (PMID 35692828, 2022). "Given the known role of CCL5 in tumour invasion, metastasis and the induction of an immunosuppressive micro-environment, targeting of CCL5-mediated pathways may offer therapeutic potential in pancreatic cancer." (PMID 33100327, 2021). "In addition, in human pancreatic cancer and mouse pancreatic tumor models (Pan02), the CCL5 level on tumor cells is elevated, while CD4+Foxp3– effector T cells preferentially express C‐C chemokine receptor 5 (CCR5)." (PMID 34977871, 2021). "Interestingly, CCL5, the cytokine we found overexpressed in AIPpos samples, recruited T-reg cells in a mouse model of pancreatic cancer." (PMID 30867568, 2019). "Thus, targeting the CD73/CCL5 axis may prove to be a promising strategy for enhancing immunotherapy efficacy in pancreatic cancer marked by hypoxia-induced immunosuppression." (PMID 37291128, 2023). "The CCR5/CCL5 chemokine axis could also have a dual role in pancreatic cancer." (PMID 35954489, 2022). "In addition, autophagic defects in mouse models of pancreatic cancer trigger the expression of pro-inflammatory cytokines such as Chemokine (C-C motif) ligand 5 (CCL5) and IL-6, and increase the infiltration of PMNs and T-cells, which fuel dysplastic transformation and tumor initiation." (PMID 32927853, 2020). "aCD40 treatment significantly increased tumoral expression of CCL5, potentially contributing to the recruitment of Granzyme B + CD4 + T cells from TDLNs to the tumor bed, as previously reported in pancreatic cancer models." (PMID 40585246, 2025). "In our study, the candidates stood out as being exceptionally strongly regulated in the cocultures over the pancreatic cancer and RAW264.7 monocultures, namely the previously discussed CCL2 and CCL22 for Panc02 cells and CCL5 for PDA6606 cells." (PMID 40282185, 2025). "Research has shown that pancreatic cancer cells recruit and reprogram macrophages through the CCL2/CCR2 signaling pathway, leading to the subsequent release of TWEAK via the CCL5/TRAF6/NF-κB pathway." (PMID 39972459, 2025).
pancreatic cancer (continued). "Doses of at least 4 Gy induced module 1 (e.g., CCL5, CXCL10) and module 4 (e.g., CCL20, CXCL8) chemokines in pancreatic cancer cells, with larger effects using higher radiation doses." (PMID 40811032, 2025). "We recently demonstrated that the RGD fiber-modified OBP-301 variant (OBP-502) induces the secretion of pro-inflammatory chemokines, CCL5 and CXCL10, from murine colorectal and pancreatic cancer cells." (PMID 39108499, 2024). "According to the TCGA and GTEx data, both CCL5 and SERPIN E1 were expressed at significantly higher levels in pancreatic cancer tissues (T, n = 179) than in nearby normal pancreatic tissues (N, n = 171)." (PMID 39516378, 2024). "The treatment of pancreatic cancer cell lines, which all expressed CCR5, with CCL5 increased the invasive potential and induced the proliferation of cells via F-actin polymerization." (PMID 38339310, 2024). "Since CCL5 is known to recruit Treg cells into the TME, we examined the immune status of maraviroc-treated pancreatic tumors." (PMID 39261943, 2024). "This is demonstrated through the successful disruption of the macrophage-CCL5-Sp1-AREG feedback loop in various models, including cell lines, PDOs, and orthotopic pancreatic carcinoma mouse models." (PMID 37553567, 2023). "In pancreatic carcinomas, IL-33 drives ILC2 activation, which promotes CD103+ dendric cell recruitment through the production of CCL-5 and, consequently, CD8+ T cell activation." (PMID 35805039, 2022). "Pancreatic cancer cell lines express high levels of CCR5, and CCL5 induced proliferation and increased the invasive potential of cancer cells." (PMID 32630699, 2020). "In this regard, our data contrast with those obtained in breast and pancreatic cancers where CCR5- and CCL5-directed treatments were equally efficient in reducing tumor progression." (PMID 22205974, 2011). "Its interaction with the ligand CCL5 promotes the migration and invasiveness of pancreatic cancer cells, and preclinical studies have shown that pharmacological blockade of CCR5 can significantly reduce tumor growth in murine models of pancreatic cancer." (PMID 41149503, 2025). "In summary, we have identified multiple cytokines as potential predictive and pharmacodynamic biomarkers for VT1021 in patients with GBM and pancreatic cancer, with PAI-1, CH13L1 and CCL5 possibly serving as both predictive and pharmacodynamic biomarkers for VT1021." (PMID 38773224, 2024). "The downregulation of CCL5 by the immunoregulatory factor 5 (IRF5) mRNA/C–C chemokine ligand 5 (CCL5) siRNA (LPR) nanoparticle combination (LPR@CHG) significantly increased M1-TAMs and modified the immune microenvironment in pancreatic cancer." (PMID 38302980, 2024). "We previously identified serum CCL5 (RANTES) as a negative prognostic marker for late-stage advanced pancreatic cancer." (PMID 39656086, 2024). "Additionally, pancreatic cancer cells expressing SDC1 can interact with T cells expressing CCL5 in the TME, promoting tumor migration, and thereby providing a potential target for immunotherapy in pancreatic cancer." (PMID 39238647, 2024). "Similar to CCL2, however, CCL5 expression is not exclusive to pancreatic cancer cells, especially as PDAC progresses." (PMID 38339310, 2024). "In this study, we find a synergistic inhibitory effect of co-targeting CD73 and immune checkpoints in pancreatic cancer and demonstrate the significant role of tumor cell-autonomous CD73 and tumor cell-autocrine adenosine–Adora2a signaling in stimulating CCL5 transcription and Treg recruitment." (PMID 37291128, 2023). "However, the role of the CCR5 ligands CCL3, CCL5 and CCL8 in pancreatic cancer remains controversial." (PMID 35954489, 2022). "Previous studies showed that CCL5 was exerted by binding to CCR5 and could promote the growth, migration and invasiveness of pancreatic cancer or HCC cells in vitro." (PMID 34899325, 2021).
pancreatic cancer (continued). "CCL5 can be secreted by a variety of tumour cells (including pancreatic cancer) as well as non-malignant stromal cells including T regulatory cells (Tregs) and macrophages." (PMID 33100327, 2021). "While the NF-κB pathway induces the upregulated expression of some chemokines such as CCL2, CCL5, CXCL5, CXCL8, CXCL10, CXCL12, and CX3CL1, it also participates in the antiapoptotic and proliferative effects of CCL5, CCL20, CXCL8, and CXCL12 in pancreatic cancer." (PMID 31991604, 2020). "Using human pancreatic adenocarcinoma and murine pancreatic tumor model, it has been found that CCR5 is highly expressed in TReg cells, while tumor cells produce elevated amount of CCL5, and disruption of CCR5/CCL5 chemokine axis blocks TReg cells migration and reduces tumor growth." (PMID 22481922, 2012). "In our study, higher baseline CCL5 levels were observed in CR/PR/SD (33.1 ng/ml) compared to PD (23.2 ng/ml), suggesting that plasmatic CCL5 may be a predictive biomarker for VT1021 in patients with GBM and pancreatic cancer." (PMID 38773224, 2024). "RNA-sequencing (RNA-seq) of pancreatic tumor lysates and principal component analysis revealed that KC;iASPPΔ8/Δ8 pancreata bear closer resemblance to KC than KPC pancreata and express greater Cd3, Cd4, Itgae, Pdcd1, Il10, Ccl5, Osm, and Cd274, reflective of an immunosuppressive stromal reaction." (PMID 36746936, 2023). "Preclinical studies also show promise for CCL5 antagonists in pancreatic cancer and bone-metastatic breast cancer, and a current phase 1 clinical trial (NCT04721301) is investigating the combination of Maraviroc with other immunotherapies in metastatic colorectal and pancreatic cancer patients." (PMID 37025604, 2023). "However, the CCL5/CCR5 axis in PDAC has been shown to correlate with promotion of migration and invasiveness of the pancreatic cancer cells, and thus, downregulation could be actually beneficial in our models." (PMID 32821382, 2020). "Notably, the T cell chemokine attractants CCL5, CXCL9 and CXCL10 were increased in DMXAA-treated tumors, macrophages and DCs, as well as KPC1242 epithelial tumor cells, suggesting that these chemokines could participate in the recruitment of T cells to STING agonist-treated pancreatic tumors." (PMID 31036082, 2019).
liver fibrosis (56 papers, 2010 to 2025). "Another well-characterized chemokine implicated in the progression of liver fibrosis is CCL5 or RANTES." (PMID 28239607, 2017). "Their shared other ligand CCL5 is known to be involved in this process, as CCL5−/− mice also showed lower degree of experimental liver fibrosis associated with reduced stellate cell activation and immune cell infiltration." (PMID 23799074, 2013). "Expression of the gene regulated on activation, T cell expressed, and secreted (RANTES; Ccl5), which is associated with severe liver fibrosis, was also significantly upregulated in HFHC-fed Dpp4–/– mice, whereas no changes in Mcp-1 (Ccl2) or Eotaxin (Ccl11) gene expression were noted." (PMID 36472923, 2023). "Furthermore, other CCRs such as CCR1 and CCR5, via CCL3/MIP1α, CCL4/MIP1β and CCL5/RANTES interaction have been implicated in liver fibrosis attributed to Ly-6Chigh monocytes recruitment or stellate cells activation, respectively." (PMID 31849997, 2019). "Specifically, NFIB is found to directly interact with the promoter region of the chemokine C─C motif ligand 5 (CCL5), suppressing its expression and thereby mitigating liver fibrosis by inhibiting oxidative stress." (PMID 41436407, 2025). "Targeting cIAPs, including BIRC3, has been suggested as a potential therapeutic strategy for liver fibrosis by increasing MMP9 expression induced by CCL5 chemotactic neutrophils." (PMID 38274787, 2023). "In this study, our steatohepatitis model demonstrated a rapid progression of hepatic fibrosis, even at 8 weeks, and pemafibrate completely suppressed Col1a1, Col1a2, and Ccl5 mRNA, which are involved in fibrosis." (PMID 35194060, 2022). "CCL5 is required for the progression of liver fibrosis by binding to CCR1 on liver macrophages and CCR5 on hepatic stellate cells." (PMID 35744024, 2022). "It has been reported that CCL5, as an inflammatory mediator, increases mainly in the acute and early stages of liver injury, and decreases as liver fibrosis gradually develops into cirrhosis in the later stages of injury." (PMID 35589690, 2022). "Deletion of the CCL5 gene, as well as pharmacological targeting of CCL5 abolishes experimental hepatic fibrosis in mice." (PMID 36012108, 2022). "This study reveals that the transcriptional Mediator subunit MED23 regulates the pathogenesis of liver fibrosis by controlling the production of inflammatory cytokines such as CCL5 and CXCL10." (PMID 31805036, 2019). "Either genetic knockout of CCL5 or pharmacological inhibition of CCL5 by the antagonist Met-CCL5 (CCL5 protein Ser24-Ser91, with an N-terminal Met) in mice ameliorated experimental liver fibrosis." (PMID 31805036, 2019). "CCR1 knockout mouse models display no alteration in wound healing, while intraperitoneal infusion of the CCL5 antagonist Met-CCL5 was shown to improve liver fibrosis in mice and accelerate regression of fibrosis." (PMID 30340330, 2018). "In fact, RANTES/CCL5 is also involved in the progression of hepatic fibrosis in mice via the triggering of CCR1 and CCR5." (PMID 26197341, 2015). "HSCs express a multitude of chemokines, including the CC chemokines CCL2, CCL3, and CCL5, which are involved in cell chemotaxis and liver fibrosis." (PMID 25076488, 2014). "CCL5 seems to be a crucial mediator of this chemokine pathway as CCL5−/− mice also show reduced liver fibrosis induced by carbon tetrachloride (CCl4) or methionine- and choline-deficient (MCD) diet." (PMID 23799074, 2013). "The CCL5 activates and recruits immune cells such as NK cells, macrophages, T cells and B cells to sites of liver inflammation by interacting with its specific receptors in the hepatic fibrosis process." (PMID 37122694, 2023). "However, further study is needed to explore the role of FASLG signaling pathway and CXCL and CCL signaling pathway(Cxcl16-Cxcr6, Ccl6-Ccr2 and Ccl5-Ccr5) in liver fibrosis of schistosomiasis." (PMID 36618421, 2022).